CD4 (CD4 molecule)
Diseases named in the same sentence as CD4 in open-access papers (continued):
Sharing a sentence is not in itself a finding about the gene and the disease.
tumor (continued). "With regard to T cells, HN molecules at the surface of infected tumor cells were shown to introduce new cell adhesive strength for interaction with lymphocytes and for T-cell costimulation, including CD4+ T helper and CD8+ cytotoxic T cells." (PMID 28531117, 2017). "Antitumor effector CD4+ T cells that respond to specific tumor-antigen stimulation were primed in TDLNs, and the majority of these tumor-specific CD4+ T cells were induced from donor CD4+ T cells." (PMID 28854279, 2017). "In fact, we have demonstrated by means of lymphocyte proliferation assay that LBC exosomes are stimulators of the immune system, inducing a potent Th1 response with tumor-specific CD4 and CD8 expansion and the production of IFN-γ." (PMID 28360912, 2017). "There was considerable variation in the total inflammatory infiltrate (INIF) (CD8+ or CD4+ and/or FoxP3+ cells in tumour region) between patients, as well as between different regions within each patient." (PMID 28961847, 2017). "LANA1 is expressed in all KSHV-infected cells, including KS tumor cells, and is a target of the cellular immune response mediated by CD4+ and CD8+ T cells." (PMID 28404899, 2017). "We and others demonstrated that tumor-reactive CD4+ T cells expanded in vitro in the presence of IL-7 exhibit superior antitumor potency upon adoptive transfer." (PMID 28939858, 2017). "Histamine produced by MCs polarizes CD4+ T Cells toward a Th2 phenotype that favors tumor development through histamine receptor type 2 (H2R)." (PMID 28467800, 2017). "MSCs profoundly reduced infiltration of macrophages, TNF-α-producing dendritic cells (DCs), TNF-α-, and IL-17-producing CD4+ T cells but increased IL-10-producing CD4+ T lymphocytes in the lungs of tumor-bearing animals." (PMID 28798777, 2017). "CEA.Tg mice bearing MC32A tumors and treated with the vaccine alone had significantly higher (*P ≤ 0.05) percentages of Ki67+/CD44+ CD4+FoxP3- T cells in the tumor microenvironment." (PMID 29088720, 2017). "Such DCs have been shown to contribute to tumor angiogenesis, the development and recruitment of immunosuppressive Tregs, and the direct suppression of CD4+ and CD8+ T cells." (PMID 29209327, 2017). "CD4+CD25+Foxp3+ Treg cells are key contributors to TGF-β-mediated immunosuppression in tumor microenvironments." (PMID 28002796, 2017). "The recently described MHC class II-restricted CD4+ cytotoxic T cells (CD4+ CTLs) emerge during chronic viral infections and during an anti-tumor response." (PMID 28850063, 2017). "Using flow cytometry, the loss of cell surface markers such as CD7, CD26, and/or CD27 on CD4+ T cells is helpful to estimate the tumor mass and to orient the choice of therapy." (PMID 28912774, 2017). "As before, CD4-AsiC-PI treatment dramatically reduced tumor growth and lung metastasis in the adoptively transferred tumor-bearing mice." (PMID 28290464, 2017). "We will first study the stability of the tumor-free fixed point and its dynamics when CD4+ T cells are administered alone." (PMID 29250133, 2017). "In the current study, we evaluated the expression of MHC-I, MHC-II (HLA-DR, -DP, and -DQ), and IFN-associated molecules in tumor cells; TIL percentage; and the number of CD4- and CD8-expressing cells in a large number of TNBC cases." (PMID 28817603, 2017). "We found that all TCR sequences identified as tumor reactive were present on both CD4+Teffs and Tregs, although with various frequencies." (PMID 28638937, 2017). "Both mechanisms likely play an important role and interestingly, both in vitro and in vivo CD4 T cell stimulations with tumour antigens have been shown to induce Treg differentiation, even in the absence of other tumour-derived immunosuppressive factors." (PMID 28239749, 2017). "It is also worth noting that the tumor immunity provided by transfer of primed CD4+ T cells is substantially enhanced when compared to the immunity provided by transfer of equal numbers of primed B cells or by transfer of primed sera." (PMID 28428886, 2017).
tumor (continued). "This was also the case for PD-L1 expression of tumor-infiltrating CD4+ and CD8+ T cells (26.5 ± 19.4% vs. 17.0 ± 12.6% and 89.4 ± 21.4% vs. 91.1 ± 12.5%, middle plot)." (PMID 28574843, 2017). "Here, we used anti-CD25-Ce6-targeted PDT, in which the anti-CD25-Ce6 complex selectively binds to tumor-infiltrated CD4+Foxp3+ Tregs and kill them locally in the tumor microenvironment by irradiation." (PMID 28537894, 2017). "It is established that an effective anti-tumor IR requires the participation of both types of T lymphocytes cells, since the CD4+ T cells are critical for the generation of tumor-specific cytotoxic T cells as well as memory T cells expansion." (PMID 29061183, 2017). "Another set of experiments that aimed to evaluate the Treg population revealed that the number of CD4+CD25+ cells was also decreased in tumor foci after treatment with IR." (PMID 28212561, 2017). "Further, these fusion genes have also been shown to stimulate expression of co-stimulatory molecules such as B7.1, CD28, and OX-40 following recombinant plasmid injection to favor anti-tumor CD4+ T-cell activation." (PMID 28304339, 2017). "We isolated IL-17A-producing Foxp3neg, IL-17A-producing Foxp3+ and IL-17Aneg Foxp3-expressing CD4+ T cells and injected the Th17 and Treg subsets in Cd45.1 tumour-bearing mice on days 5, 12 and 19 (n=4 per group)." (PMID 28290453, 2017). "We further showed that tumor-specific CD4+ and CD8+ T cells were present in the spleens of cured mice 90 days after the administration of combination therapy." (PMID 28854279, 2017). "The combined anti-CD4/anti-PD-1 mAb immunotherapy turned to be effective also on mice bearing the NXS2 tumor, as 33% of them remained tumor-free at long-term, in two independent experiments." (PMID 29070883, 2017). "Since these subsets represent a minority of the tumour-infiltrating CD4+FoxP3− cells, their exact role in the anti-tumour response is unclear." (PMID 28194010, 2017). "On the other hand, the presence of CD163+ tumor-associated macrophages, CD4+CD25+ and CD4+FoxP3+ regulatory T cells, and high ratios of regulatory T cells to CD8+ cells were associated with a worse prognosis." (PMID 29137450, 2017). "The number and infiltration pattern of CD8+ T cells were nearly identical to the number and infiltration pattern of CD3+ T cells within tumor cell nests and by far outnumbered CD4+ T in tumor samples with high intratumoral T cells infiltration." (PMID 28642820, 2017). "RNA-sequencing of blood and tumors from GBM patients revealed distinct differences between CD4+ effectors from both compartments with enrichment in multiple gene sets from tumor infiltrating PD-1—CD4+ effectors cells." (PMID 28880903, 2017). "In contrast, we did not see any effect with the non-primed splenocytes using the single vaccines and just a slight reduction of tumor cells mediated by CD4 T cells in the conditions of GM-CSF and 4-1BBL at 96 h." (PMID 28974950, 2017). "Whilst traditionally anti-tumor immune responses have been largely attributed to CD8+ T cells, increasing evidence supports a role for CD4+ T cells in the anti-tumor response." (PMID 28002789, 2017). "After immunization with cancer cells or specific peptides, tumor suppression depends on a functional CD4-positive T cell effector compartment." (PMID 28817603, 2017). "In a murine melanoma vaccine model, inhibition of both CTLA-4 or PD-1 increased the proportion of CTLA-4 and PD-1-expressing CD4/CD8 tumor infiltrating T effector cells and decreased intratumoral T regulatory cells, as compared to either agent alone." (PMID 28420805, 2017). "In sharp contrast, donor CD4+ T cells downregulated IL-7Rα upon antigen recognition in unconditioned tumor-bearing mice and IL-7Rα remained suppressed in these mice." (PMID 28939858, 2017). "In the tumor microenvironment, PD-1 expressed on Tregs accelerates CD4+ T cells differentiating into Foxp3+ Tregs under the circumstances of CD3 and TGF-β." (PMID 27974689, 2017).
tumor (continued). "Naive CD4+ T cells were more prominent in the perivascular space, whereas the majority of Tregs were far from blood vessels and localized close to the tumor parenchyma." (PMID 28290464, 2017). "The CD4+ T cell response is essential in preventing the induction of tolerance by tumor antigens, and it helps the CD8+ T cells differentiate into sustainable memory cells that can initiate antitumor immune responses." (PMID 28101811, 2017). "In MMTV-neu animals, lapatinib promotes tumor infiltration of IFNγ-secreting CD4+ and CD8+ T cells in a Stat1-dependent manner." (PMID 29403144, 2017). "In a murine model, DC treated with imatinib exhibited enhanced antigen-presenting cell function and restored the responsiveness of tolerant tumor-specific CD4+ T cells, resulting in enhanced vaccine efficacy." (PMID 28484463, 2017). "Another important consideration is that although, CD8+ T cells are canonically considered the primary cytotoxic cells involved in tumor eradication, CD4+ T cells can also kill tumor cells." (PMID 29276510, 2017). "In accordance with a previous study, we observed a delay in tumor growth and a significant difference in the observed survival (p=0.0037; CD4-depleted vs. Isotype) with the group treated with aCD4 alone." (PMID 28388572, 2017). "We report that the majority of tumor-infiltrating CD4+ and CD8+ T cells have terminally exhaustive phenotype as assessed by CD39 and PD-1 expressions." (PMID 28388539, 2017). "The increased number of CD4 T cells in fraction B treated group, is a likely reason for the observed higher tumor suppression rate." (PMID 29246138, 2017). "Depletion of CD4+ T cells partially abolished the antitumor effect leading to tumor growth in two mice after re-challenge, which indicated that the presence of CD4+ T cells was crucial for mediating the antitumor memory immunity after the treatment." (PMID 28333145, 2017). "When we divided all CD3+ cells into the different T-cell subpopulations, we observed that >80% of the CD3+ T cells were either CD4+ or CD8+ in both tumour and uninvolved pancreatic tissues." (PMID 28447602, 2017). "Antitumor immunity is initiated by antigen-presenting cells that capture tumor antigens from tumor cells and induce the CD4+ Th-1 cell/CD8+ CTL response, and they produce the antitumor cytokine IFN-γ." (PMID 28278221, 2017). "Focusing on TNBC, HDACi up-regulated PD-L1 and HLA-DR on tumor cells when co-cultured with PBMCs and down-regulated CD4+ Foxp3+ Treg in vitro." (PMID 29371976, 2017). "Tumour‐specific CD4+ T cells play an important role in the provision of help to CD8+ T cells in the tumour environment." (PMID 27324616, 2017). "Some of these DAMPs activate DCs during engulfment, which then can prime CD4+ T cells, CD8+ cytotoxic lymphocytes, and γδT lymphocytes against one or several tumor-associated antigens." (PMID 28824635, 2017). "In fact, within this study, modulation of activation-induced cell death (AICD) of tumour-infiltrating CD4+ T cells by TSA enhanced antitumour immune responses, uncovering a novel mechanism underlying the antitumour effect of HDACi." (PMID 28572863, 2017). "We previously demonstrated that CD4+ Foxp3+ Tregs elicit tumor-promoting functions during CAC in mice." (PMID 28938014, 2017). "Regarding the role of IL-22 in tumour immunity, IL-22-producing CD4 T cells were discovered in malignant pleural effusion, gastric cancer, pancreatic cancer, colorectal cancer, and B-chronic lymphocytic leukaemia." (PMID 29089667, 2017). "Further, there was significant positive correlation between survival time and peripheral CD4+ cell ratio or CD8+ cell ratio at 2 weeks after tumor inoculation." (PMID 28864944, 2017). "Both the tumor-infiltrating CD4+ and CD8+ T-cells were dominated by the effector memory phenotype (TEM, CCR7−CD45RA−, 55.52% for CD4+, 43.11% for CD8+) in GC." (PMID 29213216, 2017).
tumor (continued). "In the CD4-depleted and CD8-depleted samples, the ratios of CD8:tumor cells and CD4:tumor cells was 11.52:1 and 16.08:1, respectively." (PMID 28938530, 2017). "The activating molecules, CD40 and TLR8 ligand, seemed to enhance T cell proliferation for both CD8+ and CD4+ T cells co-cultured with tumor cells, fibroblasts and spheroid polarized MDMs stronger than the inhibiting molecules." (PMID 28750018, 2017). "In fact, PD-L1 positive expression in TIICs was positive correlated to the quantity of multiple tumor-infiltrating immune cells, such as CD4+ T lymphocytes and CD8+T lymphocytes." (PMID 28453554, 2017). "Tumour-associated macrophages (TAMs) often promote tumour progression and metastasis, whereas CD8+ cytotoxic T cells and CD4+ Th1 cells elicit antitumour immunity and suppress tumour growth." (PMID 28474673, 2017). "There was a strong positive correlation between FoxP3 and Helios expressions in the TME, and CD4+ Tregs co-expressing FoxP3 and Helios were expanded in tumor tissue compared with normal tissue and peripheral blood." (PMID 28388539, 2017). "The prevalence of FOXP3+CD4+CD56+ T cells in tumor-infiltrating lymphocytes (TILs) was moreover found to be inversely correlated with patient survival." (PMID 28791027, 2017). "CD4+ effector T cells can mediate direct tumor destruction alone or with the help from CD8+ T cells." (PMID 28101811, 2017). "It was also observed that the percentages of PD-1+, Tim-3+, and PD-1+ Tim-3+ cells among CD4+/CD8+ T-cells were significantly increased in the tumor tissues compared to their counterparts in matched peripheral blood and paraneoplastic tissues." (PMID 29213216, 2017). "PDT effectively depleted tumor infiltrated CD4+ CD25+ Foxp3+ Treg, as well as CD4+ CD25+ Foxp3- T cells that exhibit pathologic features and have a potential to become Tregs." (PMID 28537894, 2017). "Whereas we observed an immunostimulatory effect in IL-2 secretion by CD4+T cells following low dose (~20 nM) bortezomib treatment that improved anti-tumor immunity." (PMID 28052005, 2017). "The influence of T‐cells in regulating immune infiltrates within a tumor prompted us to examine if, and to what extent CD4+ and CD8+ T‐cells were affected by tumor location." (PMID 28250928, 2017). "Incipient tumor cells are removed by immune system cells; specifically, CD8+ cytotoxic T lymphocytes (CTLs) kill tumor cells, aided by CD4+ T cells." (PMID 29463952, 2017). "This coincided with a reduced tumor infiltration of CD4+ and CD8+ T cells and the inhibition of their effector functions." (PMID 28228759, 2017). "The percentage of Th17 cells (CD4+ IL-17+) in tumor-bearing mice was significantly lower, whereas the percentage of Tregs (CD25+ Foxp3+) in tumor-bearing mice was higher at 3, 5 and 7 weeks after LLC inoculation than that in Control." (PMID 29383114, 2017). "HPV16 E5 long peptide together with an E6 and E7 construct was able to reduce tumor burden in mice as well as to induce a strong and prolonged immune response, with the induction of specific T CD4+ and CD8+ cells." (PMID 28545552, 2017). "The combination of OX40L-FP and MVA-Twist-TRICOM significantly expanded the total number of CD4+Foxp3- T-cells at the metastatic tumor site (lung) by at least 2.1-fold compared to the individual treatments 28 days after tumor transplant." (PMID 29207606, 2017). "B16‐challenged Usp15−/− mice had an increased frequency of IFN‐γ+ CD4+ T cells infiltrating to the tumors, as well as a profound reduction in B16 tumors size and tumor‐induced lethality." (PMID 28544818, 2017). "This decrease in the growth rate of the tumours on the NOD background was accompanied by a marked increase in the number of CD4 T cells in the tumour-adjacent pancreatic tissue." (PMID 29113292, 2017). "To assess the functional consequences of this DC stimulation, we performed a mixed lymphocyte reaction by adding allogeneic CD4 T cells to the mixture of DC, virus, and tumor cells after 48 hr." (PMID 28345021, 2017).
tumor (continued). "Analysis of TCRs of CD4+ T cells from these mice revealed that the TCR repertoire of dominant tumor-reactive Teff clones remained rather similar in treated and non-treated mice." (PMID 28638937, 2017). "In accordance with this, EnAd-infected tumor cells showed potent stimulation of dendritic cells and CD4+ T cells in a mixed tumor-leukocyte reaction in vitro." (PMID 28345021, 2017). "In mice, tumor-derived exosomes can serve as an antigen delivery system and can prevent autologous tumor development in a CD4+ and CD8+ T cell-dependent manner." (PMID 28257101, 2017). "In contrast, there was a higher frequency of CD4+ T lymphocytes expressing CCR4 in the tumor tissue." (PMID 29020986, 2017). "This tumor-mediated modulation of immunity is demonstrated by an overall decrease of CD4+ T-cells coupled with a shift to a T helper-2 phenotype (increased expression of IL-4 and reduced expression of IL-2) in HNSCC patients." (PMID 28977830, 2017). "Our results indicate that CD4+ T cells redirected to HLA‐I‐restricted tumour antigens can kill tumour targets by a lytic granule‐mediated mechanism." (PMID 27324616, 2017). "NSG mice implanted with serially passaged tumor cells, had measurable CD4 T cells present and substantial expansion of CD8+ T cells, suggesting lymphoproliferative disease was transplantable, a hallmark of malignant transformation." (PMID 29050201, 2017). "Our previous work showed that host preconditioning with CTX allows adoptively transferred tumor-specific CD4+ T cells to differentiate into polyfunctional effector cells." (PMID 28939858, 2017). "As previously reported, the anti-CD4 mAb alone only marginally delayed tumor-progression of Neuro2a-luc-bearing mice." (PMID 29070883, 2017). "Studies have also manifested that MDSCs played a role in inhibiting anti-tumor immunity by abrogating the activation of CD4+ and CD8+ T cells, the activity of macrophages and NK cells, and the maturation of DCs." (PMID 29029545, 2017). "High levels of MHCII were also associated with higher CD8, CD4, and CD68 TIL and this was statistically significant for epithelium and stromal areas across tumor groups (i.e. all cases), and in both Luminal A, and Basal-like tumors." (PMID 27058619, 2017). "Researches revealed that tumor antigen would activate cytotoxic CD8+ T-cells which was enhanced by specific helper CD4+ T-cells." (PMID 29213216, 2017). "The lack of HLA class II (HLA‐II) expression on most tumours poses a significant obstacle to the generation of natural, on‐site tumour‐specific CD4+ T cell help." (PMID 27324616, 2017). "Here the authors show CD4+ T cells can transphagocytose bacterial and tumour antigens and present them to CD8+ T cells to activate memory and cytotoxic functions." (PMID 29147022, 2017). "The production of soluble mediators by cancer cell lines and CD4+ T lymphocytes co-cultured with tumor cells was then measured." (PMID 28846080, 2017). "The inhibiting molecules Arginase-I and iNOS only showed a slight, but non-significant cell-line dependent reversion of T cell proliferation for both CD8+ and CD4+ T cells co-cultured with tumor cells, fibroblasts and spheroid polarized MDMs." (PMID 28750018, 2017). "In the orthotopic tumor tissue, we found T cells in both the margins and the central parts of tumors; we saw both CD4+ and CD8+ cells." (PMID 28903381, 2017). "The study will monitor side effects and Ag-specificity in peripheral CD8+ and CD4+ T cell responses and tumor biopsies, which will be assessed after treatment." (PMID 28970830, 2017). "CD8+ and CD4+ T cells specific to selected tumor antigens expressed in H520 and H522 were detected in NSCLC cancer patients." (PMID 28187172, 2017). "MDSCs inhibit cytotoxic responses mediated by natural killer cells, and block the activation of tumor-reactive CD4 + T helper (CD4 + Th) cells and CD8 + T cytotoxic (CD8 + Tc) cells." (PMID 29242629, 2017).